CXCL16 (C-X-C motif chemokine ligand 16)
Diseases named in the same sentence as CXCL16 in open-access papers (continued):
Sharing a sentence is not in itself a finding about the gene and the disease.
ankylosing spondylitis (1 paper, 2024). An autoimmune chronic inflammatory disorder characterized by inflammation in the vertebral joints of the spine and sacroiliac joints. "A prior study has demonstrated that recombinant tumor necrosis factor receptor: Fc fusion protein (rhTNFR: Fc) was able to mitigate inflammation in patients with ankylosing spondylitis by inhibiting the Cxcl16/Cxcr6 pathway." (PMID 38904017, 2024).
Anxiety (1 paper, 2024). Intense feelings of nervousness, tension, or panic often arise in response to interpersonal stresses. "Collectively, our study highlights that the brain glial-derived CXCL16, promoting CXCR6+CD8+ T accumulation, acts on hippocampal neurogenesis and anxiety via TNF-α production." (PMID 39386089, 2024). "After 2 weeks of injecting anti-CXCL16 neutralizing antibodies, we evaluated anxiety-related behaviours using the OFT and EPM tests to corroborate the possible roles of the CXCL16/CXCR6 axis in the recruitment of CD8+ T cells into the brain." (PMID 39386089, 2024). "Blocking CXCL16/CXCR6 axis alleviates HBV-mediated decreased hippocampal neurogenesis and anxiety-like behaviour." (PMID 39386089, 2024). "Significantly, blocking CXCL16 in the brain or ablating peripheral CD8+ T cells mitigate the HBV-mediated downregulation of hippocampal neurogenesis and alleviates anxiety-like behaviour." (PMID 39386089, 2024).
Arthralgia (1 paper, 2021). "Unexpectedly, we found a positive correlation between miR-451 and the CXCL16 mRNA in PBMC and a lack of correlation in monocytes from RA-risk individuals with arthralgia." (PMID 33633196, 2021).
autism (1 paper, 2022). Persistent deficits in social interaction and communication and interaction as well as a markedly restricted repertoire of activity and interest as well as repetitive patterns of behavior. "The current study demonstrated that PPA-induced autism in rats was characterized by a significant increase in the expression of TNF-α, IL-6, IL-17, CCL-3, CCL-5, and CXCL-16 levels as a down-regulation of OPG in the brain of PPA-induced autism-like rats, compared to the control animals." (PMID 35334937, 2022).
B cell lymphoma (1 paper, 2023). "inoculation of murine A20 B cell lymphoma cells) contributed to the local SLC-mediated release of human CXCL16 and CCL20." (PMID 37185750, 2023).
benign adenomas (1 paper, 2019). "The protein expressions of CXCL16 were significantly increased in the PTCs compared to that of the benign adenomas (P < 0.001) or normal thyroid tissues (P < 0.001)." (PMID 31527616, 2019). "Moreover, analysis of the RNA sequencing data of the SNUH cohort, containing 81 normal thyroid tissues, 25 thyroid adenomas, and 77 PTCs showed that CXCL16 was significantly upregulated in the PTCs compared to the normal thyroid tissues or benign adenomas (P < 0.001)." (PMID 31527616, 2019).
carotid atherosclerosis (1 paper, 2025). A thickening and loss of elasticity of the walls of carotid arteries that occur with formation of atherosclerotic plaques. "Our study analysed CXCL16 and its mechanisms that contribute to pathophysiological changes during carotid atherosclerosis and plaque instability." (PMID 40165931, 2025). "Second, our research on the molecular mechanism related to the promotion of carotid atherosclerosis by CXCL16 is limited to cell experiments and lacks verification in animal models." (PMID 40165931, 2025). "This study investigated the involvement of CXCL16 in the development of carotid atherosclerosis and the related molecular mechanisms." (PMID 40165931, 2025). "However, the present studies only support the idea that CXCL16 contributes to the development of carotid atherosclerosis in humans." (PMID 40165931, 2025). "This study further elucidates the mechanism by which the inflammatory factor CXCL16 and the STAT3/NF-κB pathway participate in the inflammatory response in carotid atherosclerosis." (PMID 40165931, 2025). "Our findings indicate that CXCL16, IL-17A, and TGF-β levels can be correlated with each other, forming a positive feedback regulatory loop among the three factors and promoting the development of carotid atherosclerosis." (PMID 40165931, 2025). "Moreover, a positive feedback loop exists between CXCL16 and inflammatory factors such as IL-17A and TGF-β, mutually promoting their expression and accelerating carotid atherosclerosis progression via activation of the STAT3 and NF-κB pathways." (PMID 40165931, 2025). "To date, no studies have directly demonstrated that CXCL16 promotes the development of carotid atherosclerosis and affects its stability." (PMID 40165931, 2025).
celiac disease (1 paper, 2013). An autoimmune genetic disorder with an unknown pattern of inheritance that primarily affects the digestive tract. "Since both microbiota alterations and Th1-polarized inflammation have been linked to the pathogenesis of celiac disease, we decided to evaluate the expression of both CXCL16 and its receptor CXCR6 in this study." (PMID 23844808, 2013).
cerebral artery occlusion (1 paper, 2014). "In an in vivo model of permanent middle cerebral artery occlusion (pMCAO) we found that exogenous administration of soluble CXCL16 reduces ischemic volume and that, upon pMCAO, endogenous CXCL16 signaling restrains brain damage, being ischemic volume reduced in mice that lack CXCL16 receptor." (PMID 25071451, 2014).
chronic hepatitis B (1 paper, 2025). "This study has shown that the biomarkers GDF-15 and CCL-20 may be potential diagnostic biomarkers in detecting the presence of chronic hepatitis B, and the biomarkers CXCL-16, CCL-20, GDF-15, and CD8a may be potential diagnostic biomarkers in determining the severity of the disease." (PMID 41157623, 2025). "Our study has revealed valuable information that GDF-15, CCL-20, CXCL-16, and CD8a biomarkers, which can be measured quantitatively by a simple and cost-effective ELISA method, can be a tool that can support molecular testing (PCR) in the clinical management of chronic hepatitis B patients." (PMID 41157623, 2025). "Our study investigated four biomarkers, providing promising results that are more comprehensive and detailed for diagnosing and staging chronic hepatitis B. Each biomarker captures a different aspect of the disease: GDF-15 (stress/injury), CCL-20 (inflammation), and CXCL-16/CD8a (T cell dynamics)." (PMID 41157623, 2025).
coronary artery stenosis (1 paper, 2020). "Yi G. W. found the close relationship between the serum soluble concentration of CXCL16 and the severity of coronary atherosclerotic heart disease and the degree of coronary artery stenosis." (PMID 32676207, 2020).
disc degeneration (1 paper, 2023). "The promotion of disc degeneration by CXCL16 was found to affect fatty acid metabolism, which is consistent with previous research." (PMID 38044363, 2023). "CXCL16 was investigated by GSVA to promote disc degeneration in IDD mainly by affecting fatty acid metabolism, as demonstrated by diagnostic biomarker and immune cell correlation analysis, revealing that CXCL16 promotes disc degeneration by regulating T helper 17 cell infiltration." (PMID 38044363, 2023).
endometrioid adenocarcinoma (1 paper, 2019). An adenocarcinoma characterized by the presence of malignant glandular epithelial cells resembling endometrial cells. "OvCa TMA consisting of 33 papillary serous adenocarcinoma and 27 endometrioid adenocarcinoma tissues was stained for CXCR6 and CXCL16, the sole natural ligand of CXCR6." (PMID 30792527, 2019).
Epiretinal membrane (1 paper, 2020). An epiretinal membrane is a thin sheet of fibrous tissue on the surface of the retina along the inner limiting membrane. "Similarly, a previous study detected very low levels of CX3CL1 in the vitreous fluid of patients with epiretinal membranes and macular holes that were lower than the CXCL16 levels." (PMID 33552057, 2020).
esophageal cancer (1 paper, 2025). A primary or metastatic malignant neoplasm involving the esophagus. "In esophageal cancer, the accumulation of inflammation-derived secretory factors, including IL-6, Insulin-like growth factor-binding protein-3 (IGFBP-3), and CXC motif chemokine ligand 16 (CXCL16), results in the upregulation of CD38 in myeloid-derived suppressor cells (MDSCs)." (PMID 40382743, 2025).
gallstones (1 paper, 2023). Solid crystalline precipitates in the biliary tract, usually formed in the gallbladder, resulting in the condition of cholelithiasis. "Hepatic CXCL16 mRNA and protein levels are increased in gallstones accompanied by liver injury." (PMID 36636609, 2023). "The serum concentration of CXCL16 is positively correlated with the activities of ALT and AST in patients with gallstones." (PMID 36636609, 2023).
gastroduodenitis (1 paper, 2016). "For example, in H. pylori positive gastroduodenitis we demonstrate increased serum levels of chemoattractants for mononuclear lymphocytes, such as CXCL10, CCL22, and CXCL16." (PMID 28018296, 2016).
graft-vs-host disease (1 paper, 2021). "Nevertheless, CXCL16 can also cause graft-vs-host disease (GvHD) due to its participation in the recruitment of activated CD8+ T cells into the liver, leading to GvHD-induced hepatitis." (PMID 33800554, 2021).
hepatitis B (1 paper, 2025). "ROC analysis showed that CXCL-16 values had poor but statistically significant diagnostic value for predicting hepatitis B in patients (p < 0.05, AUC = 0.629)." (PMID 41157623, 2025). "We investigated the diagnostic properties of quantitative values of the biomarkers CCL-20, CXCL-16, CD8a, and GDF-15 in predicting hepatitis B using ROC curve analysis." (PMID 41157623, 2025).
Hodgkin’s disease (1 paper, 2018). "CXCL16 is expressed in a variety of tissues and cells, including activated endothelial cells, Hodgkin’s disease-derived tumor cells, and MΦ.7,8 However, the role of CXCL16 in macrophage polarization remains unknown." (PMID 29588487, 2018).
Hyperglycemia (1 paper, 2023). An increased concentration of glucose in the blood. "Decreased ADAM10 and increased CXCL16 protein expression could be a protective response for podocytes against hyperglycemia through the scavenging of oxidated LDL by CXCL16." (PMID 37513824, 2023).
hyperthyroidism (1 paper, 2025). Overactivity of the thyroid gland resulting in overproduction of thyroid hormone and increased metabolic rate. "The two genes demonstrated good diagnostic efficacy in the hyperthyroidism validation set GSE276271 (AUC: TMEM127, 0.636; CXCL16, 0.591) and in the AF validation set GSE2240 (AUC: TMEM127, 0.745; CXCL16, 0.720)." (PMID 41357074, 2025). "Two machine learning algorithms, LASSO and RF, were employed to identify CXCL16 and TMEM127 as biomarkers significantly associated with both hyperthyroidism and AF." (PMID 41357074, 2025). "In the hyperthyroidism validation dataset, CXCL16 and TMEM127 achieved area under the curve (AUC) values of 0.636 and 0.591, respectively, while in the AF validation dataset, the values were 0.745 and 0.720, demonstrating their diagnostic potential for both diseases." (PMID 41357074, 2025). "CXCL16 and TMEM127 are promising biomarkers, offering insights into the shared pathogenesis of hyperthyroidism and AF." (PMID 41357074, 2025). "RT–qPCR analysis demonstrated that CXCL16 and TMEM127 expression levels were significantly elevated in both the hyperthyroidism and AF groups compared to the control group, aligning with the findings from our prior bioinformatics analysis." (PMID 41357074, 2025). "RT–qPCR analysis revealed that the expression levels of CXCL16 and TMEM127 were significantly elevated in both the hyperthyroidism and AF groups compared to the control group, corroborating the results of our bioinformatics analysis." (PMID 41357074, 2025). "The results demonstrated that the gene expression levels of CXCL16 and TMEM127 were significantly upregulated in both the hyperthyroidism and AF groups compared to the control group." (PMID 41357074, 2025). "Although no direct studies have established a link between CXCL16 and hyperthyroidism, its crucial role in immune regulation and inflammation suggests potential involvement in immunopathological processes of hyperthyroidism." (PMID 41357074, 2025).
inflammatory brain diseases (1 paper, 2021). "Generally, CXCL16 concentrations are increased in inflammatory brain diseases." (PMID 34804996, 2021).
Intraventricular hemorrhage (1 paper, 2024). Bleeding into the ventricles of the brain. "Three out of seven ELANE/CXCL16-treated E13.5 embryos showed intraventricular hemorrhage." (PMID 39349662, 2024).
invasive ductal carcinomas (1 paper, 2019). "CXCL16 expression was found to be higher in stroma samples of invasive ductal carcinomas compared to normal adjacent stroma." (PMID 31698786, 2019).
kidney cancer (1 paper, 2024). Primary or metastatic malignant neoplasm involving the kidney. "In patients with UCa the median urinary concentration of CXCL16 was distinctly higher than in other cancers, whereas we observed a slight increase of CXCL16 in the urine of kidney cancer patients, too." (PMID 39587670, 2024). "With regard to CXCL16, we also observed a slight increase of CXCL16 in the urine of kidney cancer patients when compared to non-cancer patients." (PMID 39587670, 2024).
knee osteoarthritis (1 paper, 2025). "The CXCL16 rs2277680 GG + GA genotype is associated with the effectiveness of metformin versus placebo in overweight patients with knee osteoarthritis." (PMID 40050290, 2025).
lactic acidosis (1 paper, 2008). Metabolic acidosis characterized by the accumulation of lactate in the body. "Genes induced by lactic acidosis included: PLAUR, ERBB3, CD55, interleukin 15, CXCL16, angiogenin and MHC class I genes." (PMID 19057672, 2008).
lentivirus infection (1 paper, 2024). Virus diseases caused by the Lentivirus genus. "Further, we identify CXCL10 and CXCL16 as important molecular drivers of inflammatory pathways specifically in response to highly pathogenic Lentivirus infection." (PMID 38317183, 2024).
leukemia (1 paper, 2024). A malignant (clonal) hematologic disorder, involving hematopoietic stem cells and characterized by the presence of primitive or atypical myeloid or lymphoid cells in the bone marrow and the blood. "Here, we found that in the B-ALL microenvironment, IL-17A secreted by Th17 cells promoted the proliferation and survival of B-ALL cells and increased the secretion of the chemokine CXCL16 by leukemia cells." (PMID 38172124, 2024). "The cytokine IL-17A, derived from Th17 cells, promotes Ph+ B-ALL progression and increases CXCL16 expression in leukemia cells." (PMID 38172124, 2024). "CXCL16 dramatically increased the percentage of Th17 cells in the BM, spleen, LNs and PB, indicating that CXCL16 promotes the migration of Th17 cells to the leukemia niche in vivo." (PMID 38172124, 2024). "Treatment with an anti-CXCL16 neutralizing antibody (anti-CXCL16) significantly inhibited the migration of Th17 cells and the proliferation activity of leukemia cells." (PMID 38172124, 2024). "To exclude the possibility that the increase in CXCL16 accumulation in the spleens of B-ALL mice was due to the high leukemia burden, we measured CXCL16 expression on a per-cell basis in primary B-ALL cells after rmIL-17A treatment by FACS." (PMID 38172124, 2024). "Here, we show that Th17 cells and IL-17A are highly elevated in Ph+ B-ALL patients, which in turn promote the progression of Ph+ B-ALL by activating BCR-ABL, IL6/JAK/STAT3 and NF-kB signalling pathways and increasing the secretion of the chemokine CXCL16 by leukemia cells." (PMID 38172124, 2024). "We then investigated how IL-17A stimulated the secretion of CXCL16 from leukemia cells." (PMID 38172124, 2024). "In this study, we showed that IL-17A could induce secretion of the chemokine CXCL16 in the leukemia niche by promoting the nuclear translocation and subsequent activity of NF-κB." (PMID 38172124, 2024). "In addition, IL-17A-activated Ph+ B-ALL cells secrete the chemokine CXCL16, which in turn promotes Th17 differentiation, attracts Th17 cells and forms a positive feedback loop supporting leukemia progression." (PMID 38172124, 2024). "On day 21 after treatment, anti-CXCL16 treatment reduced leukemia cell infiltration in the spleen; the spleen weight; the populations of immature blast cells in the PB and spleen; the percentages of B220dim CD19+ cells in the PB, BM, spleen and LNs; and the percentage of Ki-67+ cells in the spleen." (PMID 38172124, 2024). "However, the exact role of CXCL16 in Th17 cell differentiation and function, especially in the leukemia niche microenvironment, remains uncharacterized." (PMID 38172124, 2024). "We found that the depletion of CXCL16 with an anti-CXCL16 neutralizing antibody attenuated leukemia progression and decreased the frequency of Th17 cells in the leukemia niche in vivo, suggesting that IL-17A mediates leukemia progression by promoting CXCL16 secretion." (PMID 38172124, 2024). "Moreover, anti-CXCL16 treatment significantly reduced the percentages of Th17 cells in the BM, spleen, LNs and PB of B-ALL cell-transplanted mice, indicating that anti-CXCL16 treatment impeded the migration of Th17 cells to the leukemia niche in vivo." (PMID 38172124, 2024). "Furthermore, we determined the percentage of Th17 cells in the leukemia niche in mice with secondary BCR-ABLtTA B-ALL cell transplantation treated with or without CXCL16." (PMID 38172124, 2024).
leukocytosis (1 paper, 2025). "Positive correlations between CXCL16 and CRP, leukocytosis, neutrophils, and NLR were confirmed (0.67; 0.46; 0.48; 0.54, respectively)." (PMID 41373861, 2025).
Lewis lung carcinoma (1 paper, 2025). "To investigate the impact of CAF-derived CXCL16 in MPE progression in vivo, we used a murine MPE model using Lewis lung carcinoma cells (LLCs)." (PMID 41310104, 2025).
malignant glioma (1 paper, 2016). A grade III or grade IV glioma arising from the central nervous system. "Apart from its physiological expression, CXCL16 is pathologically expressed in cancer cells of different origin including malignant glioma cells and reactive astrocytes in situ and in vitro." (PMID 27784296, 2016).
myeloid leukemia (1 paper, 2025). A clonal proliferation of myeloid cells and their precursors in the bone marrow, peripheral blood, and spleen. "CXCL16/SR-PSOX, a class G scavenger receptor, is upregulated in human myeloid leukemia mononuclear cells (THP-1) when incubated in plasma from RA patients, with increased uptake of Ox-LDL and subsequent formation of foam cells." (PMID 40943434, 2025).
myeloma (1 paper, 2014). "We do not know the mechanism that leads to the release of CXCL16 from glia, however it has been recently reported that activation of the purinergic receptor P2X7 induces CXCL16 shedding from RPMI8226 myeloma B cells." (PMID 25071451, 2014).
myocardial diseases (1 paper, 2016). "The proinflammatory function of CXCL16 in myocardial diseases is supposed to be mainly mediated by interaction with the corresponding receptor CXCR6." (PMID 26499307, 2016).
myocardial ischemia (1 paper, 2021). A disorder of cardiac function caused by insufficient blood flow to the muscle tissue of the heart. "There was indeed research deeming CXCL16 can have athero-protective effect but might make plaque unstable, yet CXCR6 can prevent myocardial ischemia." (PMID 34046056, 2021).
myositis (1 paper, 2022). "CXCL16 was significantly elevated in the two disease groups, which supports the notion that CXCR6 signaling is crucial in myositis." (PMID 36330424, 2022).
Nephropathy (1 paper, 2025). A nonspecific term referring to disease or damage of the kidneys. "Notably, T cells in kidney biopsies from PyV-associated nephropathy patients express CXCR6 and transcriptional analysis shows significant upregulation of CXCR6 and CXCL16." (PMID 40043065, 2025).